SERPINA1 (serpin family A member 1)
Diseases named in the same sentence as SERPINA1 in open-access papers (continued):
Sharing a sentence is not in itself a finding about the gene and the disease.
tumor (continued). "This sustained induction under defined stress conditions in culture provides strong evidence that SERPINA1 is part of a targeted survival response in tumor cells, rather than a passive reflection of systemic inflammation." (PMID 41467954, 2025). "Interestingly, the transcriptomic analysis showed that the spheroid co-culturing, compared to separate mono-cultures of HT-29 and fibroblasts, induced upregulation of INHBA, SerpinA1 and S100A9, which are well-known players in tumor biology." (PMID 39011470, 2024). "Within an epithelial cell cluster, SERPINA1 shows elevated expression surrounding one of the tumor regions but not the others." (PMID 37426750, 2023). "In addition, acute phase proteins (ORM1, CRP, SAA1) and complement cascade components (SERPINA1, C5, FGA) showed an obviously significant correlation with tumor size, reflecting a positive connection between inflammatory response and tumor size." (PMID 37460463, 2023). "On the contrary, HSPA1A, SERPINA1 and CXCL1 are highly expressed in tumor tissues." (PMID 37950156, 2023). "It is interesting to note that this analysis did not indicate any predicted activation relationships; rather, relationships related to inhibition (for seven proteins: LMNA, NME1, PKM, S100A4, SERPINA1, VIM, and AHCY) were indicated for both increased and decreased proteins in the tumor." (PMID 35512017, 2022). "Both CCNE1 (p < 0.001) and PLK1 (p < 0.001) showed higher expression in tumor tissue than in normal tissue, while the expression of SERPINA1 in both tumor and normal tissue was not significantly different (p = 0.541)." (PMID 36393842, 2022). "On the protein level, we validated these hub genes expressions of normal tissues and tumor tissues through the HPA database.HSPA8 and HSPB8 expressed higher in tumor tissues than that in normal tissues, while SERPINA1 and DIRAS3 expressed higher in normal tissues against tumor tissues." (PMID 34876005, 2021). "ADAM9 and SERPINA1 expression between tumour and tumour adjacent normal tissue were not significantly different (p = .634.491, respectively)." (PMID 34187256, 2021). "pegRNA Ctnnb1 S45 deletion-treated animals showed extensive tumor formation, whereas pegRNA SERPINA1-treated animals did not induce any tumor formation." (PMID 33837189, 2021). "Intriguingly, levels of serum AAT do not correlate with levels of C-reactive protein, neutrophils-to-leukocyte ratio, and do not correlate with SERPINA1 expression or AAT staining in the tumor tissue." (PMID 31487965, 2019). "According to our findings, higher serum levels of AAT in NSCLC patients are prognostic for the patient’s worse outcome but do not correlate with SERPINA1 expression in tumor or non-tumor lung tissue or with staining intensities for tumor-related AAT protein." (PMID 31487965, 2019). "Some studies have shown that patients with SERPINA1 expression in their tumor cells have worse prognosis than those without expression." (PMID 31487965, 2019). "The Kaplan Meier survival analysis based on the ratio between relative SERPINA1 expression in tumor and paired non-tumor lung tissue confirmed that overall and disease-free patient`s survival is better when tumor vs non-tumor ratio for SERPINA1 is higher." (PMID 31487965, 2019). "So far, the associations between clinical prognosis of NSCLC patients and SERPINA1 expression and AAT levels in tumor and adjacent non-tumor tissues as well as serum AAT concentrations have not been reported." (PMID 31487965, 2019). "The better overall survival of the patients was related to higher SERPINA1 expression in the tumor but lower expression in non-neoplastic tissue." (PMID 31487965, 2019). "The Kaplan-Meier curves based on the ratio between relative SERPINA1 expression in tumor and in paired lung tissue show that overall and disease-free patient’s survival is better when tumor vs non-tumor ratio for SERPINA1 expression is >0.26-fold." (PMID 31487965, 2019).
tumor (continued). "Although the mechanism of serpinA1 in tumor progression is not fully elucidated, it has been shown to promote lung colonization via fibronectin assembly." (PMID 26015410, 2015). "We also provided evidence that Snail and serpinA1 induced CRC cell invasion and migration by upregulation of fibronectin, as well as migration of other cancer cells, demonstrating a novel signaling mechanism involved in tumor progression." (PMID 26015410, 2015). "In summary, while SERPINA1 elevation post-TACE occurs within an inflammatory context, our data collectively position it not as a passive bystander, but as a key effector molecule that is co-opted by residual tumor cells to drive a specific resistance program against the selective pressures of TACE." (PMID 41467954, 2025). "However, there was no change in cardiac SerpinA1 expression following the heterotopic heart transplant of an MI model, which also reported enhanced tumor growth." (PMID 38279150, 2024). "During the chronic inflammation, which is a driving force in tumor development, SERPINA1 expression and AAT levels increase substantially and, together with other inflammatory molecules, may activate tissue repair responses, induce proliferation of premalignant cells and enhance their expansion." (PMID 31487965, 2019). "Thus, systemic inflammation and tumor microenvironment may reflect higher tumor/non-tumor expression ratio of SERPINA1 gene." (PMID 31487965, 2019). "A selection of the proteins from this panel are of high abundance in plasma (i.e., C3 and SERPINA1), while others are not (i.e., PF4 and ECM1), and so reflect the contributions of localized changes due to tumor presence and anti-tumor immunity." (PMID 35008327, 2021). "In the eight experimental groups, SERPINA1 knockdown reversed ITGB3 overexpression-induced effects, normalizing PCNA/Vimentin elevation and E-cadherin suppression (P < 0.05), establishing ITGB3 as the primary effector of SERPINA1-mediated tumor progression." (PMID 41467954, 2025). "Since tumor tissue used for SERPINA1 expression analysis contains not only tumor but also other cell types expressing SERPINA1 gene, we performed immunostainings for AAT protein in tumor tissues." (PMID 31487965, 2019).
cancer (134 papers, 1987 to 2026). A tumor composed of atypical neoplastic, often pleomorphic cells that invade other tissues. "Extensive research underscores the utility of AAT and the SERPINA1 gene as prognostic or diagnostic indicators in a variety of cancer types, as demonstrated by a comprehensive body of research." (PMID 39851516, 2025). "The ICBatlas analysis revealed the conserved bidirectional pattern (protective MAOB/SERPINA1 vs. risk-enhancing IGFBP2/LGR6) of the four-gene signature as a pan-cancer theoretical framework for risk stratification." (PMID 40821817, 2025). "Lastly, tissue-specific splicing variation is known for SERPINA1 in alpha-1 antitrypsin deficiency, but its function in cancer is unclear." (PMID 38069324, 2023). "Their findings show that the SERPINA1 gene does not only reflect inflammatory responses associated with cancer formation but also plays an important role in NSCLC pathogenesis." (PMID 37501182, 2023). "Although the splicing events of these genes were not reported previously, their gene expression level was linked to tumorigenesis or prognosis of CRC (SERPINA1) or other cancer types (ARHGEF9, CHEK1, HKDC1)." (PMID 32503434, 2020). "Genetic variants of SERPINA1 have been linked to increased risk for conditions such as large artery atherosclerotic stroke, and high expression of the protein has been associated with poor prognosis in several cancers, including lung and colorectal." (PMID 41270070, 2025). "SerpinA1 has been reported to promote and be associated with outcomes in various types of cancer." (PMID 38279150, 2024). "In contrast, in other cancers, SERPINA1 is associated with poor prognosis." (PMID 39851465, 2024). "Serpin family A member 1 (SERPINA1) encodes a protease inhibitor participating in many human diseases, but its value in immunoregulation and prognosis of human cancers remains unclear." (PMID 37511325, 2023). "Then, the association between SERPINA1 expression in cancer tissues and the prognosis was analyzed." (PMID 37511325, 2023). "Conversely, in HIV-negative patients, cancer tissues displayed elevated SERPINA1 expression (Figure 6A5, A6) relative to matched adjacent controls (Figure 6A7, A8)." (PMID 41584047, 2026). "While elevated SERPINA1 expression correlates with adverse clinical outcomes in diverse cancers, its functional role in HCC, particularly in the context of TACE resistance, remains largely unexplored." (PMID 41467954, 2025). "In oncology, SERPINA1 exhibits altered expression across cancer types, with significant heterogeneity among immune and molecular subtypes." (PMID 40821817, 2025). "The results indicated that TACSTD2, ENTPD1, and SERPINA1 have some predictive ability for other cancer types, such as ATC and FTC, but their predictive power is not as strong as it is for PTC." (PMID 40520228, 2025). "Through a comprehensive bioinformatics examination, SERPINA1 has also been identified as a potential therapeutic target for osteosarcoma, underscoring the versatility and breadth of its applicability in cancer treatment." (PMID 39851516, 2025). "Next, we detected the relationship between SERPINA1 expression and immune subtypes and molecular subtypes of human cancers via the TIMER database and the R package." (PMID 37511325, 2023). "Our findings showed that SERPINA1 was upregulated in most cancer tissues except CHOL, LIHC, LUAD, LUSC, ACC, DLBC, and THYM." (PMID 37511325, 2023). "Although we performed a systematic analysis on the role of SERPINA1 in pan-cancer, and cross-certified the result through different databases and R package, the study has some limitations." (PMID 37511325, 2023). "Our results, obtained from the Xiantao web tool and Kaplan–Meier plotter database, demonstrated that SERPINA1 expression in tissues had a significant prognostic value for many cancers." (PMID 37511325, 2023).
cancer (continued). "Cancer cells can destroy surrounding tissues through releasing elastase, plasmin, and cathepsin, then spread locally, while SERPINA1 protein (A1AT) can inactivate these enzymes." (PMID 37511325, 2023). "In this study, through comprehensive analysis of data from The Cancer Genome Atlas (TCGA) datasets, we found that SERPINA1 was dysregulated in many cancers compared with normal tissues." (PMID 37511325, 2023). "For example, spots enriched with TM4SF1, PRSS1/2, and SERPINA1 are also predicted to, respectively, have high proportions of Cancer clone A cells, Acinar cells, and Ductal centroacinar cells." (PMID 37550279, 2023). "For example, Serpin Family A Member 1 (SERPINA1) encodes for alpha-1 antitrypsin (A1AT) protein, which regulates the invasive and metastatic capacities of various cancers like lung, gastric, and CRC." (PMID 37950156, 2023). "Previous research confirmed serum SERPINA1 as a potential biomarker for cancer diagnosis and prognosis." (PMID 37511325, 2023). "Based on the findings above, we considered SERPINA1 a potential prognostic biomarker or a novel therapeutic target for immunotherapy in human cancers." (PMID 37511325, 2023). "The results above demonstrated that SERPINA1 expression is closely related to the immune and molecular subtypes of various cancers." (PMID 37511325, 2023). "Our results found that SERPINA1 expression was associated with TMB and MSI in some cancers, positively or negatively, indicating that SERPINA1 plays a different role in the prediction of immunotherapy effect in various human cancers." (PMID 37511325, 2023). "The differential expressions and prognostic values of SERPINA1 in different cancers were explored comprehensively." (PMID 37511325, 2023). "The need for mouse models to upregulate the expression of all Serpina1 paralogues simultaneously is of particular importance since there is evidence to suggest that overexpression of AAT is most probably involved in cancer related processes." (PMID 36357523, 2022). "SERPINA1 was proposed to be useful to monitor evolution of NSCLS reflecting individual cancer progression." (PMID 35512017, 2022). "It was reported that in patients with carcinomas, SERPINA1 enhances the invasive and metastatic abilities of carcinomas in gastric cancer, colorectal carcinoma, and lung cancer and indicates poor prognosis of patients with colorectal cancer." (PMID 36349191, 2022). "In fact, cancer cells grown in serum containing media were always positive for AAT protein independently of SERPINA1 expression levels." (PMID 31487965, 2019). "This suggests that, although SERPINA1 has the potential to be a valuable marker in BC, its role may vary according to the type of cancer." (PMID 39851465, 2024). "Furthermore, SERPINA1 expression in most of these cancers was also related to disease-specific survival (DSS)." (PMID 37511325, 2023). "Above all, SERPINA1 shows potential value for the diagnosis and prognosis of many human cancers and may be involved in the immune regulation of the TME." (PMID 37511325, 2023). "The results confirmed that SERPINA1 expressions in different immune subtypes and molecular subtypes of most cancers were significantly different, indicating that SERPINA1 may affect the immune microenvironment and cancer prognosis." (PMID 37511325, 2023). "The results above suggested that genomic alteration of SERPINA1 occurs in cancers, and differential SERPINA1 expression might regulate cancer progression." (PMID 37511325, 2023). "Further study about SERPINA1 is necessary for cancer immunotherapy and prognosis." (PMID 37511325, 2023). "Different immune subtypes of various cancers showed different SERPINA1 expressions." (PMID 37511325, 2023). "In addition, the core genes IGFBP1, FBN1, and SERPINA1 selected in this study have also been reported to be involved in the regulation of cancer cell migration and invasion." (PMID 34692659, 2021).
cancer (continued). "We found pathogenic/likely pathogenic variants in cancer-related genes that could contribute to the BC and TC phenotype (e.g., MUTYH c.1187G>A and SERPINA1 c.1096G>A)." (PMID 32443704, 2020). "Further literature search reveals that SERPINA1 is a known marker for good prognosis in cancer." (PMID 26158350, 2015). "The serum levels of serpinA1 are higher in cancer patients than in healthy patients." (PMID 26015410, 2015). "Serpina1, a major inhibitor of human serine proteases in serum, is produced mainly by the liver, but also by extra-hepatic cells, including neutrophils and certain cancer cells." (PMID 18218118, 2008). "Currently, the mutational status of SERPINA1 in BC and other cancers is not fully elucidated." (PMID 39851465, 2024). "Above results suggested that SERPINA1 might be important in cancer immunotherapy." (PMID 37511325, 2023). "Our results based on the SangerBox database demonstrated that SERPINA1 expression was significantly connected to ICP genes in most cancer types, especially GBMLGG, OV, KIPAN, and PRAD, which suggested that patients with these cancers may respond well to ICB treatment." (PMID 37511325, 2023). "Hsa-miR-744, which regulates SERPINA1 and JUN, has been found to be elevated in various cancers, with significant implications for prognosis." (PMID 39893248, 2025). "SERPINA1 expression is positively related to ICP genes in most cancer types, especially GBMLGG, OV, KIPAN (Pan-kidney cohort), and PRAD, in which more than 90% of 60 ICP genes were connected to SERPINA1 expression." (PMID 37511325, 2023). "Through the SangerBox database, we demonstrated that SERPINA1 was positively connected to immune scores, stromal scores, and ESTIMATE scores in many cancers." (PMID 37511325, 2023). "For example, SERPINA1 expression was closely related to CD4+ T cells, CD8+ T cells, neutrophils, and macrophages in most cancer types." (PMID 37511325, 2023). "The expression of SERPINA1 and SORT1 has previously been shown to be increased in several types of cancers; however, the two proteins served as two protective biomarkers in the current study." (PMID 36765702, 2023). "Protective mechanisms included defense against infection (Alpha-1-B glycoprotein A1BG, Serpin family A member 1 SERPINA1, Transthyretin TTR), neuroprotection (TTR), and reduced risks of inflammation, infections, and cancer (SERPINA1, Keratin 10 KRT10)." (PMID 36145440, 2022). "Experiments in vitro revealed that external AAT and/or overexpressed SERPINA1 gene significantly enhanced cancer cell migration, colony formation and resistance to apoptosis." (PMID 35853971, 2022). "Several upregulated genes (LRP1, SERPINA1, HRG, ILK, CAV1, and LAMA4) identified in our study are involved in GEM resistance in human cancer 23-28." (PMID 35281857, 2022). "Serpin peptidase inhibitor clade A member 1 (SERPINA1), a protease inhibitor plays an important role in a variety of cancers." (PMID 34692659, 2021). "Several studies have showed that SERPINA1, APOA1, VCAN, and APOB mediated the development of cancer chemotherapy resistance." (PMID 34737677, 2021). "Additional experiments in vitro revealed that external AAT and/or overexpressed SERPINA1 gene significantly improve cancer cell migration, colony formation and resistance to apoptosis." (PMID 31487965, 2019). "Remarkably, both cancer cells, independently on SERPINA1 expression levels, have taken up exogenous AAT which was found to be localized in cytosol." (PMID 31487965, 2019). "To evaluate the pan-cancer robustness of our 4-gene signature (MAOB, IGFBP2, SERPINA1 and LGR6), we leveraged the ICBatlas database—comprising 93,000+ patients across 18 cancer types (including 12 cancers with multi-omics profiling) and 30 immune checkpoint inhibitor (ICI) treatment cohorts." (PMID 40821817, 2025).